IAPP (islet amyloid polypeptide)
Diseases named in the same sentence as IAPP in open-access papers (continued):
Sharing a sentence is not in itself a finding about the gene and the disease.
Insulin resistance (continued). "In vitro and in vivo studies have shown that β-cells activate the UPR following exposure to high glucose; fatty acids - especially when saturated; increased functional demand (as in the context of insulin resistance); or insulin and islet amyloid polypeptide (IAPP) misfolding/aggregation." (PMID 33967960, 2021). "Some authors have hypothesised that the formation of IAPP aggregates plays a critical role in the transition from early-stage insulin resistance to overt T2DM." (PMID 33467592, 2021). "Dietary supplementation with curcumin reduced circulating levels of IAPP and GSK-3β, thus suggesting a novel mechanism through which curcumin could potentially be used for alleviating insulin resistance related markers for reducing the risk of T2D and AD." (PMID 32283762, 2020). "IAPP was reported to be involved insulinoma, insulin resistance." (PMID 24344781, 2013). "In addition, it has been observedthat IAPP administration induces insulin resistance in rats, although nosuch effect was evident in humans." (PMID 18497871, 2008). "When we instead analyzed the change in IAPP concentration between baseline and after 3 months of diet (changes further on), we again noted a positive correlation with BMI as well as insulin and insulin resistance, glucose, and several interleukins, but a negative correlation with NfL." (PMID 39062913, 2024). "Moreover, an animal study also showed that amylin could suppress insulin secretion by enhancing β-cell apoptosis, which consequently induced hepatic and extrahepatic insulin resistance and glucose dysregulation in human IAPP transgenic rats." (PMID 21935471, 2011). "It has been hypothesized that TPTD-induced impaired insulin resistance may be due to an increased intracellular free calcium concentration, leading to a decrease in insulin-dependent glucose transport, downregulation of insulin receptors, and increased islet amyloid polypeptide (IAPP) levels." (PMID 33801212, 2021). "Furthermore, islet amyloid polypeptide (IAPP) and S-100A8 N-terminal peptide also induce insulin resistance in vitro." (PMID 34831299, 2021). "IAPP, a pancreatic beta cell peptide, can evoke insulin resistance by antagonising insulin in a non-competitive manner." (PMID 32283762, 2020). "These deposits consist of islet amyloid polypeptide (IAPP).Considering the pathogenetic similarities and the 90% structural similarity between Aβ precursor protein and IAPP, it should not be surprising that AD seems to be predisposed to insulin resistance, insulin hypersecretion, and T2DM." (PMID 21876656, 2008).
Hyperglycemia (34 papers, 2014 to 2026). An increased concentration of glucose in the blood. "Studies have also shown that mAb generated from biopsies of T2D patients, which recognize pathogenic IAPP aggregates, prevent hyperglycemia and IAPP fibril formation in mouse model." (PMID 40927754, 2025). "In fact, genetically modified rodent models expressing human IAPP demonstrate aggressive diabetic-like phenotype, such as insulin impairments and hyperglycemia, with IAPP deposits and β-cell loss." (PMID 31293412, 2019). "Although hyperglycemia may not be the only driver of diabetic neuropathy, it may predispose to IAPP-induced hypersensitivity because hIAPP-induced cell toxicity is exacerbated by hyperglycemia-induced glycated insulin." (PMID 36917177, 2023). "Furthermore, hyperglycemia induces ER stress by causing the accumulation of poorly folded/unfolded proteins (e.g., misfolded-proinsulin, IAPP) in pancreatic β-cells." (PMID 33918379, 2021). "In fact, recent studies have revealed a complex interplay between chronic hyperglycemia, oxidative stress, and misfolding of IAPP, which together contribute to β-cell dysfunction in T2D." (PMID 41225798, 2025). "Activation of inflammasomes by islet amyloid polypeptide, hyperglycemia or autophagy insufficiency can lead to pancreatic β-cell dysfunction or apoptosis in T1D." (PMID 35365229, 2022). "Systemic metabolic disturbances, e.g., hyperglycemia, or islet-derived local factors, e.g., ATP released from stressed β-cells or accumulation of IAPP (islet amyloid polypeptide), can thereby trigger the initial islet inflammation." (PMID 32709161, 2020). "β-Cells are capable of producing chemokines (e.g., MCP1/CCL2) in the presence of high FFA levels, and hyperglycemia forces β-cells to produce islet amyloid polypeptide (IAPP)." (PMID 28168202, 2017). "Moreover, chronic hyperglycemia increases proinsulin and islet amyloid polypeptide (IAPP) synthesis in β-cells, leading to the accumulation of misfolded proteins and enhanced generation of reactive oxygen species (ROS) via oxidative protein folding processes." (PMID 40430501, 2025). "Although the cause of neuropathy in T2DM is not fully understood, three characteristics of T2DM may contribute to the development of diabetic neuropathy: hyperglycemia, obesity, and amyloidogenic IAPP." (PMID 36917177, 2023). "Although high titers of anti-IAPP antibodies were obtained, hyperglycemia and loss of β-cell mass were not prevented." (PMID 32131431, 2020). "While preventing hyperglycemia is favorable, reducing IAPP might abolish IAPP’s physiological role to induce satiety, a feature that was not assessed." (PMID 32131431, 2020). "Furthermore, since T2D is characterized by oxidative stress, which is exacerbated by both hyperglycemia and amyloid-induced toxicity, antioxidant agents may complement strategies aimed at inhibiting α-amylase and α-glucosidase or preventing IAPP aggregation." (PMID 41225798, 2025). "However, it is considered that PDAC may lead to DM through releasing cancer cell mediators stimulating hyperglycaemia or β-cell dysfunction and enhancing insulin resistance, such as adrenomedullin, islet amyloid polypeptide." (PMID 38067280, 2023). "However, overexpression of human IAPP (h-IAPP) in rodent models promotes amyloid deposits, beta-cell dysfunction and apoptosis, consequently leading to reduced beta-cell mass and hyperglycemia, supporting the role of h-IAPP as a contributor to the islet pathology in human T2D." (PMID 34069914, 2021). "Vaccination of IAPP transgenic mice against amyloidogenic aggregates of IAPP prevented the formation of IAPP aggregates in pancreatic islets in vivo, delayed the onset of amyloid-induced hyperglycemia and reduced local inflammation while restoring insulin production." (PMID 32131431, 2020).
Hyperglycemia (continued). "In addition, chronic hyperglycemia increases proinsulin biosynthesis and formation of IAPP in the beta cells which leads to accumulation of misfolded IAPP and ROS production, disruption of ER Ca2+ homeostasis, activation of the UPR pathways leading to proinsulin degradation and beta cell death." (PMID 30386256, 2018). "In conclusion, our data show that human IAPP induces signs of peripheral neuropathy in the absence of hyperglycemia and aggravates mechanical allodynia in hyperglycemic obese (Ob/Ob) mice." (PMID 36917177, 2023). "We propose that the increased susceptibility of T2D patients to developing PD may not be primarily due to hyperglycemia, but rather due to insulin resistance or the interaction between IAPP and α-synuclein and/or tau." (PMID 39847072, 2025). "Rodent studies show the formation of IAPP aggregates precedes β-cell dysfunction and the clinical signs of disease, suggesting that hyperglycaemia may not be a prerequisite for islet amyloid formation." (PMID 28754022, 2017).
Parkinson disease (23 papers, 2013 to 2025). A progressive degenerative disorder of the central nervous system characterized by loss of dopamine producing neurons in the substantia nigra and the presence of Lewy bodies in the substantia nigra and locus coeruleus. "Islet amyloid polypeptide (IAPP) is involved in more than 30 protein misfolding diseases like Parkinson’s disease, Huntington’s disease and T2DM." (PMID 39273348, 2024).
insulinoma (16 papers, 2011 to 2025). "Here, we aimed to evaluate IAPP immunohistochemically in islets or insulinoma cells in association with clinical characteristics." (PMID 39028826, 2024). "Insulinoma is another panNET showing abundant stroma which is composed of amyloid derived from hypersecretion and deposition of amylin (also known as islet amyloid polypeptide—IAPP)." (PMID 40668487, 2025). "Higher IAPP staining was observed in the insulinoma cells of patients 3 and 6 (respectively) than in those of patients 1 and 4 (respectively) or in patients 2 and 5 (respectively), both of whom had no history of hypoglycemic coma." (PMID 39028826, 2024). "Islet amyloid polypeptide (IAPP) is a factor that regulates food intake and is secreted from both pancreatic islets and insulinoma cells." (PMID 39028826, 2024). "In this study, we immunohistochemically evaluated pancreatic IAPP staining in six insulinoma patients and six control patients to enhance our understanding of IAPP regulation in persistent hyperinsulinemia and hypoglycemia." (PMID 39028826, 2024). "In this study, we first found that the staining level of IAPP tended to be reduced immunohistochemically in the human islets of insulinoma patients, another IAPP-mediated mechanism for escaping hypoglycemia." (PMID 39028826, 2024). "The other study demonstrated that CPC decreased apoptosis induced by islet amyloid polypeptide in rat insulinoma β INS-1E cells by reducing oxidative stress and regulating JNK and p38 MAPK pathways." (PMID 36501143, 2022). "We used OFFGELTM proteomics to study how IAPP exposure affects the proteome of rat pancreatic insulinoma Rin-5F cells." (PMID 30419808, 2018). "Regarding IAPP, it was reported that depletion of cholesterol from plasma membrane of rat insulinoma cells inhibits the internalization of oligomers, which in turn potentiates IAPP cytotoxicity." (PMID 26576436, 2015). "In contrast, overexpression of pitrilysin protects insulinoma cells from human islet amyloid polypeptide-induced apoptosis." (PMID 26191799, 2015). "In conclusion, we observed that immunohistochemically detected IAPP staining in the islets of insulinoma patients was decreased, which might represent a novel form of IAPP regulation under persistent hyperinsulinemia and hypoglycemia." (PMID 39028826, 2024). "Since pitrilysin is a mitochondrial protein, we used immunofluorescence staining of pancreases from human IAPP transgenic mice and Western blot analysis of IAPP in isolated mitochondria from insulinoma cells to provide evidence for a putative intramitochondrial pool of IAPP." (PMID 26191799, 2015). "We observed that the IAPP staining level and percentage of IAPP-positive beta cells tended to be lower (p = 0.1699) in the islets of insulinoma patients than in those of control patients, which might represent a novel IAPP expression pattern under persistent hyperinsulinemia and hypoglycemia." (PMID 39028826, 2024). "Insulinomas express AMY, and AMY or islet amyloid polypeptide (IAPP) has been detected in endocrine tumors (e.g., pancreatic tumors producing insulin or glucagon) and human pancreas." (PMID 36980580, 2023). "It was initially named insulinoma (or islet) amyloid peptide (IAP), which soon changed to islet amyloid polypeptide (IAPP) since the abbreviation IAP was already used." (PMID 21486192, 2011). "The IAPP staining levels in islets in the nontumor area of insulinoma patients were weaker than that in the islets from the control patients." (PMID 39028826, 2024). "In insulinoma cells when pitrilysin expression was decreased to 5% of normal levels, there was a 60% increase in islet amyloid polypeptide-induced apoptosis." (PMID 26191799, 2015).
insulinoma (continued). "In this study, the IAPP staining levels in islets of the nontumor areas in the insulinoma patient samples tended to be lower than those in the control patient samples, and the staining level was especially low in the samples of patients who had experienced severe hypoglycemia." (PMID 39028826, 2024). "First, we focused on IAPP staining in islets in the nontumor area of insulinoma patients." (PMID 39028826, 2024). "IAPP, also known as amylin, is a 37-amino acid peptide of the calcitonin gene family isolated from amyloid deposits of non-insulin-dependent diabetic pancreas and insulinomas." (PMID 36551213, 2022). "In addition, we could not directly evaluate the intensity of IAPP staining levels in islets or insulinoma cells." (PMID 39028826, 2024).
type 1 diabetes (16 papers, 2014 to 2026). "In T1D (type 1 diabetes), β-cell stress is mediated by autoimmunity however the cause of β-cell stress and dysfunction in T2D is not yet fully resolved, but protein misfolding and the formation of toxic oligomers of the islet amyloid polypeptide (IAPP) are emerging as important contributors." (PMID 36430204, 2022). "A small but growing body of research also links IAPP-mediated proteotoxic stress to the pathogenesis of type 1 diabetes and to the functional decline of transplanted islets." (PMID 41977193, 2026). "One of the CGRP family peptides, islet amyloid polypeptide (IAPP), is an important autoantigen in type 1 diabetes." (PMID 36189304, 2022). "Plasma levels of IAPP and insulin deviate in a subpopulation of young with newly-diagnosed type 1 diabetes." (PMID 24671002, 2014). "Plasma IAPP levels in children and adolescents with newly diagnosed type 1 diabetes (n = 224) were analysed and concentrations exceeding 100 pmol/L (127.2 – 888.7 pmol/L) were found in 11% (25/224)." (PMID 24671002, 2014). "Congo red merged islet amyloid polypeptide was also seen in pancreatic biopsies of patients with type 1 diabetes, suggesting that the formation of these aggregates may be induced by enteroviruses." (PMID 34695168, 2021). "Elevated plasma proinsulin/C-peptide and proIAPP/IAPP ratios are promising biomarkers of beta cell dysfunction, can potentially be used to predict the onset of type 1 diabetes, islet graft failure, and response to immunotherapy, and may be associated with loss of PC1/3 expression in islets." (PMID 39404844, 2024). "Increasing evidence suggested that the islet amyloid polypeptide (IAPP) is an essential autoantigen in the pathogenesis of type 1 diabetes (T1D) in humans and non-obese diabetic (NOD) mice." (PMID 36032077, 2022).
Obesity (12 papers, 2016 to 2025). Accumulation of substantial excess body fat. "At the center of this inflammatory process is the NLRP3 inflammasome, an intracellular sensor activated by a wide range of metabolic danger signals that accumulate in obesity, including saturated fatty acids (e.g., palmitate), ceramides, uric acid, high glucose, and islet amyloid polypeptide (IAPP)." (PMID 40943225, 2025). "Indeed, inhibition of autophagy compromises β-cell survival and leads to dysregulation of glucose homeostasis in response to diet-induced obesity and/or increased expression of human islet amyloid polypeptide (hIAPP)." (PMID 35428762, 2022). "Next, we investigated whether processing deficits in IAPP mediate the observed obesity phenotype." (PMID 35963866, 2022). "In the case of obesity-related pancreatic inflammation that is common in T2D, an abundance of free fatty acids (FFA), reactive oxygen species (ROS), islet amyloid polypeptide (IAPP), and proinflammatory cytokines increase M1-like macrophage polarization." (PMID 33256225, 2020). "Studies in nonobese healthy individuals or people with or without obesity or T2D using hyperglycemic clamps showed that endogenous IAPP does not affect insulin sensitivity." (PMID 39998445, 2025). "Our findings indicate that prophylactic vaccination with IAPP and its derivative IAPP7-19-TT, protects wild-type female mice, but not males, from obesity-induced early mortality, and the derivative showed a strong trend for prolonging the lifespan of Tg females but not males." (PMID 27379014, 2016).
protein misfolding diseases (12 papers, 2017 to 2024). "T2D is considered a protein misfolding disorder associated with the accumulation of islet amyloid polypeptide (IAPP) in pancreatic islets." (PMID 31316720, 2019). "In this study we aimed to identify protein segments with similarity to Aβ, αSyn and IAPP, three highly amyloidogenic proteins with important roles in protein misfolding diseases." (PMID 38223341, 2024). "The islets of Langerhans in T2D have the classical hallmarks of a protein misfolding disorder with amyloid deposits of a locally expressed protein, islet amyloid polypeptide (IAPP)." (PMID 36814640, 2023). "Accumulating evidence suggests that toxic aggregates of islet amyloid polypeptide (IAPP), commonly known as amylin, may make a significant contribution to β-cell dysfunction and T2D, it is classified as a protein misfolding disease (PMD)." (PMID 28754022, 2017).
Autoimmunity (7 papers, 2019 to 2025). The occurrence of an immune reaction against the organism's own cells or tissues. "The proteasome is a critical component of cellular protein homeostasis, and its dysfunction could amplify the effects of IAPP misfolding, linking it to mechanisms that may underlie beta-cell failure and autoimmunity in DM1." (PMID 39859479, 2025). "The protective function from localized and systematic autoimmune disorders should be distinguished as exemplified in Aβ and IAPP." (PMID 31993048, 2019). "It seems likely that IAPP aggregates, by inducing islet inflammation, may be a trigger or accelerator of autoimmunity in T1D." (PMID 36983153, 2023).